PBX1 (PBX homeobox 1)
Diseases named in the same sentence as PBX1 in open-access papers (continued):
Sharing a sentence is not in itself a finding about the gene and the disease.
ovarian carcinoma (19 papers, 2012 to 2025). A malignant neoplasm originating from the surface ovarian epithelium. "In ovarian cancer, the association of PBX1 and proliferation was observed to be NOTCH3-dependent, and PBX1-mediated chemoresistance to be related to PBX1 binding to STAT3 promoter, positively regulating its transcription." (PMID 38404687, 2024). "PBX1 operates as oncogene in various tumors, including myoepithelioma and ovarian cancer, and our data now extends its pathogenic role to HL." (PMID 33539429, 2021). "TCRS-417 (T417) is a small molecule compound that effectively inhibits the self-renewal and proliferation of ovarian cancer stem cells by targeting PBX1 and interfering with the interaction of PBX1–DNA." (PMID 39090090, 2024). "Nevertheless, dysregulation of these cellular processes can occur in malignant diseases, as PBX1 has been shown to be altered in several cancer types, including gastric cancer, lung cancer, lymphoma, ovarian cancer, and esophageal squamous cell carcinoma." (PMID 38877653, 2024). "The Notch intracellular domain 3 (NICD3)/CSL complex transcriptionally activated the expression of PBX1 by directly binding to the PBX1 promoter segment harbouring the CSL‐binding sequence in ovarian cancer (OC) cells." (PMID 35068042, 2022). "An analysis of Pbx1 expression in ovarian tumor samples indicated that Pbx1 was upregulated in these samples, and the overexpression of Pbx1 led to platinum-based chemotherapy resistance in patients with ovarian cancer." (PMID 33402862, 2020). "It was also reported that notch receptor 3 (NOTCH3) is a transcriptional activator of Pbx1 in ovarian cancer." (PMID 33402862, 2020). "In this report, we focused on one of the homeobox genes, PBX1, which was found to play a critical role in ovarian cancer, with the intent of identifying and characterizing its transcriptional network in cancer cells." (PMID 22567123, 2012). "Here, we applied an integrated approach by overlapping PBX1 ChIP-chip targets with the PBX1-regulated transcriptome in ovarian cancer cells to identify genes whose transcription was directly regulated by PBX1." (PMID 22567123, 2012). "Previous studies have demonstrated that PBX1 was essential for cell growth in ovarian cancer cells including OVCAR3; here, we performed siRNA knockdown to determine if MEOX1 knockdown produced a phenotype similar to PBX1 knockdown." (PMID 22567123, 2012). "We further determined if PBX1 target genes identified in ovarian cancer cells were co-overexpressed with PBX1 in carcinoma tissues." (PMID 22567123, 2012). "The recently available TCGA ovarian serous cancer dataset permitted us to perform statistical analysis to determine the co-upregulation of PBX1 and its target genes in ovarian carcinomas." (PMID 22567123, 2012). "Our result showing that MEOX1 expression reversed the growth inhibitory effect of PBX1 knockdown suggests that MEOX1 mediates the growth-supporting function of PBX1 in ovarian cancer cells." (PMID 22567123, 2012). "The results demonstrated that ovarian carcinoma has a high level of PBX1 expression as compared to the other 8 types of cancers." (PMID 22567123, 2012). "Moreover, T417 represents a novel potential agent that targets PBX1, thereby inhibiting CSCs in ovarian cancer." (PMID 37853437, 2023). "Interactions between MEIS1 and PBX1–3 are involved in the early stages of ovarian cancer." (PMID 33402862, 2020). "In addition, Meox1 was overexpressed in ovarian cancer cells along with Pbx1, and the silencing effects of Pbx1 were reversed by Meox1 expression in the cell lines." (PMID 33402862, 2020). "al. suggests that this transcription factor partially mediates PBX1 signaling in ovarian cancers." (PMID 27285982, 2016). "In addition, Pbx1 and DLGAP5 have been identified as direct target genes of Notch3 in ovarian cancer, and knockdown of either target with shRNAs led to reduced cell proliferation and, in the case of Pbx1 knockdown, impaired tumor formation." (PMID 25366565, 2014).
ovarian carcinoma (continued). "From this perspective, it would be important to determine if MEOX1 modulates the selectivity and target sequence binding affinity of the PBX1 transcription complex in ovarian cancer, and ultimately, it would be interesting to determine how PBX1/MEOX1 complex formation promotes oncogenesis." (PMID 22567123, 2012). "Since overexpression of PBX1 and MEOX1 is relatively specific to ovarian cancer as compared to other solid tumors, the biological significance of PBX1 and MEOX1 co-expression and their cooperation in transcriptional regulation are likely to be context- and tissue-dependent." (PMID 22567123, 2012). "In ovarian cancer, MEOX1 has been reported to function as a cofactor of pre-B-cell leukemia homeobox-1 (PBX1), mediating the cancer-promoting biological behavior of PBX1." (PMID 38486335, 2024). "PBX1 is the direct downstream target gene of the NOTCH3 signaling pathway, which is necessary for ovarian cancer cell survival and proliferation." (PMID 35041720, 2022). "mRNA expression of EFNB2 and PBX1 in IOSE, FTSEC and human ovarian cancer cell lines were also analysed by qRT-PCR." (PMID 33652749, 2021). "In our study, the c-Kit-mediated upregulation of cancer stemness-related Notch3—PBX1 and β-catenin—ABCG2 signaling pathways and promotion of ovarian cancer tumorigenicity and drug resistance were all phospho-PHBY259 dependent." (PMID 32169072, 2020). "PBX1, a stem cell reprogramming factor, has been observed to promote CSC-like phenotypes, including resistance to platinum in ovarian cancer cells." (PMID 32046751, 2020). "However, whether this increase in PBX1, a stem cell reprogramming factor in ovarian cancer chemoresistance, is primarily responsible for the drug resistance of ovarian cancer cells to carboplatin or requires the cooperation of other factor(s) remains to be elucidated." (PMID 32169072, 2020). "An ovarian cancer cell line, OVCAR3, was selected because this cell line was previously reported to overexpress PBX1, and was dependent on PBX1 expression for cellular survival." (PMID 22567123, 2012). "PBX1 further upregulates the signal transducer and activator of transcription 3 (STAT3) expression through transcription, thereby enhancing the resistance of ovarian cancer cells to carboplatin." (PMID 39090090, 2024). "In summary, we have shown that the association of c-Kit with PHB upregulated phospho-PHBY259 in the lipid raft domain, resulting in subsequent activation of the Notch3—PBX1 and β-catenin—ABCG2 signaling pathways to increase stemness, tumorigenicity and drug resistance in ovarian cancer." (PMID 32169072, 2020).
B-cell acute lymphoblastic leukemia (11 papers, 2012 to 2025). A neoplasm of lymphoblasts committed to the B-cell lineage, typically composed of small to medium-sized blast cells. "Chromosomal rearrangements involving PBX1 have been identified and reported in pre-B-cell acute lymphoblastic leukemia development, in line with the role of this gene." (PMID 41300798, 2025).
gastric cancer (11 papers, 2017 to 2026). A primary or metastatic malignant neoplasm involving the stomach. "The introduction of a missense mutation in PBX1 is sufficient to avoid tumorigenesis in gastric cancer cells." (PMID 36833200, 2023). "Initial PBX1 is associated with cancers of the hematopoietic system, which are followed by solid tumors such as neuroblastoma, renal carcinoma, gastric cancers, and esophageal cancers." (PMID 37006624, 2023). "Finally, the dominant-negative effects observed in gastric cancer cells after the introduction of a missense mutation in PBX1 may also rely on the fact that the mutant gene was introduced through infection techniques, leading to a more stable expression." (PMID 36833200, 2023). "The TCGA database showed that PBX1 levels were dramatically lower in CRC tissues than in normal tissues which was contrary to gastric cancer." (PMID 36739270, 2023). "We have previously reported that PBX1 is upregulated in gastric cancer and functions as an oncogene that promotes tumor proliferation and metastasis." (PMID 36739270, 2023). "rs6426881 at pre-B cell leukemia transcription factor 1 (PBX1) 3′UTR was associated with poor prognosis in breast and gastric cancer by altering the affinity of miR-522-3p to PBX1." (PMID 35628648, 2022). "Along with these, PBX1 over-expression led to a higher number of in vitro colonies in gastric cancer cell lines; PBX1 was indeed found to be upregulated in patients’ samples and to promote gastric cancer cell proliferation and invasion through promoting miR-650 transcription." (PMID 38404687, 2024). "Overexpression of PBX1 abolishes the effects of miR-650 inhibitors on gastric cancer cells." (PMID 39129784, 2024). "At variance with the previously quoted tumor-inducing role in this type of cancer, other authors reported overexpression of the PBX1 inhibitor PBXIP1 in gastric cancer patients, leading to repressed PBX1 transcriptional activity and promotion of cell proliferation, migration, and invasion." (PMID 38404687, 2024). "Contradictory roles of PBX1 are also present in the framework of gastric cancer." (PMID 38404687, 2024). "Our previous study showed that PBX1 promotes proliferation and metastasis in gastric cancer." (PMID 36739270, 2023). "Although this protein has been shown to contribute to cellular development and tumorigenesis, the role of PBX1 in gastric carcinoma (GC) remains unclear." (PMID 28514754, 2017).
lymphoma (11 papers, 2013 to 2025). A malignant (clonal) proliferation of B- lymphocytes or T- lymphocytes which involves the lymph nodes, bone marrow and/or extranodal sites. "B-lymphoblastic leukemia/lymphoma with TCF3::PBX1 fusion is typically strongly positive for CD9, dim-to-negative for CD34, and dim-to-negative for CD20." (PMID 40227608, 2025). "Information concerning the role of PBX1 in adult lymphomas remains limited, requiring further research." (PMID 41226583, 2025). "B-lymphoblastic leukemia/lymphoma with TCF3::PBX1 fusion has also been reported to overexpress CD58 and CD81 when compared with cases of B-lymphoblastic leukemia/lymphoma without cytogenetic alterations or with other cytogenetic abnormalities." (PMID 40227608, 2025). "The TCF3/PBX1 gene fusion is a recurrent genetic abnormality in pediatric B-lymphoblastic leukemia/lymphoma (B-ALL/LBL)." (PMID 31575852, 2019). "There is a paucity of data regarding the role of PBX1 in the development of lymphomas." (PMID 41226583, 2025). "Thus, the continued presence of PBX1 positivity in mature B-cells may promote lymphoma formation." (PMID 41226583, 2025). "E2A-PBX1 induces proliferation in fibroblasts in culture or T-progenitor lymphoma in transgenic mice through a mechanism that does not require DNA binding mediated by the PBX1 homeodomain." (PMID 26098938, 2015).
acute leukemia (8 papers, 2010 to 2024). A clonal (malignant) hematopoietic disorder with an acute onset, affecting the bone marrow and the peripheral blood. "Pbx1 is a product of a proto-oncogene that was originally discovered in acute leukemia and critically regulates organogenesis and hematopoiesis." (PMID 27387666, 2016).
lung carcinoma (8 papers, 2017 to 2025). "PBX1 also plays a critical role in lung cancer by regulating the expression of invasive transcription factors SMAD3 and Fos-associated antigen 1, involved in metastasis, through its interaction with PREP1." (PMID 39129784, 2024). "PBX1 has also been reported to promote EMT induction in lung cancer; however, its role in EMT during GC remains to be elucidated." (PMID 28514754, 2017). "Four of the IEAA-associated SNPs (rs2736100 in TERT, rs2275558 in PBX1, rs144317085 in TET2, and rs2492286 in RPN1) were associated with 16 unique traits including multiple cancers (e.g., lung cancer, glioma) and blood cell counts (e.g., platelet count, eosinophil count, red blood cell count)." (PMID 34187551, 2021). "It has been demonstrated previously that the other hub mRNAs (PBX1, PLIN2, and TPSAB1) are closely related to the progression of lung cancer and COPD by regulating the cell cycle and cell proliferation." (PMID 39940682, 2025). "Meanwhile, PBX1 was also reported to attenuate HF-MSC senescence and apoptosis by alleviating ROS-mediated DNA damage, as well as the ROS production regulation in lung cancer cells." (PMID 36361531, 2022). "Furthermore, PBX1, in conjunction with PREP1, can induce epithelial to mesenchymal transitions (EMT) and lung cancer metastasis by increasing the TGF-β-induced SMAD3 nuclear signal." (PMID 28514754, 2017).
lupus (8 papers, 2011 to 2024). "The abnormal development of T cells and B cells caused by the abnormal expression of PBX1 is related to the occurrence of systemic lupus erythematosus." (PMID 39129784, 2024). "Except for the clinical manifestations and conventional laboratory tests, 10 age- and sex-matched SLE patients without NPSLE and normal controls were recruited to analyze the expression of PBX1, a lupus susceptibility gene, in peripheral blood B cells." (PMID 37352070, 2023). "This impaired Pbx1-d-mediated T cell homeostasis has consequences on lupus associated atherosclerosis, with chimeric atherosclerosis-prone mice carrying Pbx1-d expressing T cells developing more severe lesions than mice carrying Pbx1-b expressing T cells." (PMID 35693798, 2022). "However, the underlying mechanism of PBX1 in the pathogenesis of demyelination in lupus remains unclear and requires further exploration." (PMID 37352070, 2023). "Moreover, we propose that the lupus susceptibility gene PBX1 may serve as a potential biomarker for the clinical diagnosis and treatment of SLE-DS." (PMID 37352070, 2023). "In lupus murine model with B cell-specific deletion of pbx1, the downregulation of PBX1 in autoimmune B cells has been linked to the exacerbation of systemic lupus erythematosus (SLE)." (PMID 39129784, 2024). "The Pbx1-d dominant-negative isoform is more commonly expressed in CD4+ T cells from lupus patients than in those from healthy controls." (PMID 31440232, 2019). "Pbx1-d is related to autoreactive T cell production in mice with the Sle1a1 lupus vulnerability locus." (PMID 31440232, 2019). "We have previously shown that this process was defective in T cells from lupus-prone mice expressing the novel isoform of the Pbx1 gene, Pbx1-d." (PMID 21708033, 2011). "Based on the homology between murine and human PBX1, we investigated the expression of PBX1-d, the isoform over-expressed in the NZM210 allele, in lupus patients' CD4+ T cells." (PMID 21708033, 2011). "In addition, PBX1 might be a potential biomarker for the clinical diagnosis of lupus in patients with demyelinating syndrome." (PMID 37352070, 2023). "By positional cloning, we have determined that Pbx1 regulates the production of autoreactive CD4+ T cells and the size of the Treg compartment in the NZM2410 lupus model." (PMID 21708033, 2011). "Moreover, The expression of lupus susceptibility gene PBX1 in CD19+ B cells was lowest in demyelinating syndromes with lupus patients compared with healthy volunteers and lupus patients without demyelination, and its relative expression negatively correlated with SLE disease activity." (PMID 37352070, 2023). "We found that PBX1 expression, which was negatively correlated with SLE disease activity, was lowest in CD19+ B cells from SLE-DS patients than lupus without demyelination and normal controls." (PMID 37352070, 2023).
prostate carcinoma (8 papers, 2008 to 2024). A carcinoma that arises from epithelial cells of the prostate gland. "In summary, we have identified androgen related gene TMPRSS2 that is regulated by SREBF1, PBX1 and ETS family members that are associated with the prostate cancer and gene TMPRSS2 has been found in 80% of tumor experiments." (PMID 20025723, 2009). "In this context, previous publications demonstrated that USP9x-dependent stabilization of insulin receptor substrate 2 or the transcription factors PBX homeobox 1 and ERG supported prostate cancer growth and metastasis." (PMID 37173959, 2023).
non-small cell lung carcinoma (7 papers, 2013 to 2025). A group of at least three distinct histological types of lung cancer, including non-small cell squamous cell carcinoma, adenocarcinoma, and large cell carcinoma. "Mutations in PBX1 have recently been detected in non-small-cell lung cancer and this gene is now being considered as a target for therapy and prognosis." (PMID 25170874, 2014). "In non-small cell lung cancer PBX1 was recently shown to inhibit tumor growth; in patients’ tissues it is indeed downregulated through binding to the ubiquitin ligase TRIM6, which drives PBX1 proteasomal degradation." (PMID 38404687, 2024). "The transcription factor PBX1 is regarded as an oncogene in various cancers, but its role in non-small cell lung cancer (NSCLC) and the detailed mechanism is not known." (PMID 37324936, 2023).
Parkinson disease (7 papers, 2012 to 2021). A progressive degenerative disorder of the central nervous system characterized by loss of dopamine producing neurons in the substantia nigra and the presence of Lewy bodies in the substantia nigra and locus coeruleus. "PBX1 is responsible for the protection of dopaminergic neurons from oxidative stress and reduced levels of nuclear PBX1 were associated with Parkinson’s disease in humans." (PMID 34490028, 2021). "Our result suggests that rs8070723 G allele might influence MAPT expression level by reducing the binding affinity of upstream regulatory protein PBX1, therefore providing a mechanistic association with neurodegenerative diseases including Progressive Supranuclear Palsy and Parkinson’s Disease." (PMID 31001319, 2019). "Animal models of PBX1 (PBX Homeobox 1) have pointed to Parkinson’s disease." (PMID 32327964, 2020). "Interestingly, PBX1 transcriptional network has been reported to be involved in controlling dopaminergic neuron development and is impaired in Parkinson's disease." (PMID 31487305, 2019). "PBX1 encodes a nuclear protein that belongs to the PBX homeobox family of transcriptional factors, and studies suggested PBX1 regulates the patterning of the cerebral cortex and its transcriptional network controls dopaminergic neuron development in Parkinson’s disease." (PMID 31001319, 2019). "Therefore, Pbx1 may be important in determining the vulnerability of mesDA neurons to degeneration during the early phases of Parkinson’s disease." (PMID 22748019, 2012). "It was revealed that Pbx1 provides a beneficial effect of protecting against oxidative stress by increasing Nfe2l1 (also called NRF1), and decreasing levels of both TFs were found in midbrain dopaminergic neurons of Parkinson's patients." (PMID 31584878, 2019).
B cell acute lymphoblastic leukaemia (6 papers, 2014 to 2024). "First described in 199076, 77 as an alternate partner of chromosomal translocation in human pre‐B‐cell acute lymphoblastic leukaemia, several physiological and pathological functions of PBX1 have been elucidated." (PMID 38877653, 2024). "Lastly, the PBX1 gene encodes a nuclear protein that belongs to the PBX (Pre-B cell leukaemia transcription factor) homeobox family of transcriptional factors and is involved in a chromosomal translocation in human pre-B cell acute lymphoblastic leukaemia." (PMID 34680511, 2021).